MRGPRX2 (MAS related GPR family member X2)
Diseases named in the same sentence as MRGPRX2 in open-access papers (continued):
Sharing a sentence is not in itself a finding about the gene and the disease.
rosacea (15 papers, 2019 to 2025). A chronic erythematous skin disorder that affects the face. "TSLP, a key type 2 cytokine implicated in chronic skin inflammation, has recently been linked to MRGPRX2 activation, which is also associated with the pathogenesis of rosacea." (PMID 41296102, 2025). "LL-37 expression is upregulated in patients with chronic inflammatory skin conditions such as rosacea, suggesting that mast cell activation via MRGPRX2 may be responsible for the symptoms associated with this disease." (PMID 32038646, 2019). "Recent evidence shows higher expression of mast cell receptor MRGPRX2/MRGPRB2 in rosacea patients’ skin tissues and its potential as a novel drug target." (PMID 41296102, 2025). "By combining in vivo and in vitro models, the present study aimed to provide a comprehensive understanding of the therapeutic potential of MRGPRX2/B2 antagonist GE1111 in LL-37-induced rosacea-like inflammation." (PMID 41296102, 2025). "We evaluated the therapeutic effect of a novel small-molecule MRGPRX2/MRGPRB2 antagonist in a mouse model of rosacea and itch." (PMID 41296102, 2025). "Our study provided in-depth phenotypic and mechanistic evidence on the protective effect of novel MRGPRX2/B2 antagonist GE1111 in attenuating LL-37-induced rosacea-like inflammation and compound 48/80-induced itch in mice." (PMID 41296102, 2025). "We used LL-37 as a prototype MRGPRX2/B2 agonist to induce rosacea symptoms in mice and modulate the immune microenvironment in vitro." (PMID 41296102, 2025). "We utilized human cathelicidin LL-37, known to play a role in rosacea’s pathogenesis, as an MRGPRX2/B2 agonist." (PMID 41296102, 2025). "We evaluated the effect of MRGPRX2/B2 antagonist GE1111 on a mice model of LL-37-induced rosacea-like inflammation and also validated the effect by using MR K/O mice." (PMID 41296102, 2025). "The C48/80 model’s relevance to rosacea pruritus lies in its MRGPRX2-dependent pathway, supported by studies linking compound 48/80 to mast cell-mediated itch in inflammatory skin conditions." (PMID 41296102, 2025). "Tissue-specific protein analysis is a priority for future studies incorporating acute and chronic toxicity studies and clinical specimens are required to support the translational potential of MRGPRX2/B2 antagonist GE1111 in rosacea." (PMID 41296102, 2025). "LL37, in conjunction with neuropeptides (NPs), another key mediator involved in the pathogenesis of rosacea, can activate MCs through the Mas-related G protein-coupled receptor member X2 (MRGPRX2, mouse homologue MrgprB2)." (PMID 37626650, 2023). "Release of chemokines by neuropeptides via MRGPRX2 promotes neurogenic inflammation and mast cell activation in rosacea." (PMID 38193038, 2023). "Elevated expression of MRGPRX2 has been reported in skin MCs of patients with allergic contact dermatitis, chronic spontaneous urticaria, rosacea, and mastocytosis." (PMID 36275683, 2022). "The authors proposed that osthole allosterically modulates MRGPRX2, and perhaps MrgprB2, to prevent LL-37-induced rosacea in mice." (PMID 36275683, 2022). "We measured the inflammatory surge and MRGPRX2/B2 signalling pathway in vivo model of rosacea." (PMID 41296102, 2025). "A recent discovery in mast cell activation is the role MRGPRX2 in rosacea mouse models." (PMID 38193038, 2023).
chronic spontaneous urticaria (11 papers, 2019 to 2025). "for an important involvement of MRGPRX2 is the observed increased sensitivity to provocation with exogenous and endogenous MRGPRX2 agonists in patients with chronic spontaneous urticaria." (PMID 39996342, 2025). "Increased numbers of MRGPRX2+ MCs were seen in lesional skin of patients with MC-driven disorders, such as chronic spontaneous urticaria, chronic prurigo and cutaneous mastocytosis." (PMID 38022672, 2023). "Expression of MRGPRX2 is upregulated in human skin MCs of patients with chronic idiopathic urticaria when compared to healthy individuals." (PMID 31652731, 2019). "This increased sensitivity to MRGPRX2 agonists may be due to the increased number of MRGPRX2 expressing cells (i.e. mast cells) observed in the skin of patients with chronic spontaneous urticaria, but also in many other chronic inflammatory skin diseases." (PMID 39996342, 2025). "This has drawn attention to IgE-independent mechanisms of mast cell activation, particularly in drug hypersensitivity reactions and chronic spontaneous urticaria, where MRGPRX2 was found to be upregulated in skin mast cells of patients with severe course of disease." (PMID 38812508, 2024). "Intradermal administration of substance P induced greater wheal reactions in patients with chronic spontaneous urticaria than in healthy subjects, suggesting that substance P/MRGPRX2-mediated mast cell degranulation is an alternative pathway for induction of chronic spontaneous urticaria." (PMID 35874756, 2022). "In addition to these acute responses, MRGPRX2 also contributes to complex chronic diseases of the skin, including chronic idiopathic urticaria (CIU) and AD." (PMID 33429916, 2021). "Indeed, overexpression of MRGPRX2 and/or increased numbers of MRGPRX2+ MCs have been described in the lesions of patients with MC-driven disorders, e.g., cutaneous mastocytosis, chronic spontaneous urticaria (CSU), and chronic prurigo, and correlated with disease severity in the latter." (PMID 35958589, 2022). "Because MRGPRX2 is now recognized as the mast cell receptor for basic secretagogues, there is currently a tremendous interest in whether MRGRPX2 could play an important role in various pruritic dermatoses such as chronic spontaneous urticaria." (PMID 39493768, 2024).
Pruritus (8 papers, 2023 to 2026). Pruritus is an itch or a sensation that makes a person want to scratch. "Interestingly, enhanced expression of MRGPRX2 as well as gain-of-function mutations have been associated with diseases linked to pruritus." (PMID 41516211, 2025). "Our preliminary findings align with previous studies using C48/80-induced itch and MRGPRX2/B2 involvement." (PMID 41296102, 2025). "As the model demonstrates MRGPRX2-specific effects; broader pruritus models are needed for comprehensive anti-itch assessment." (PMID 41296102, 2025). "Subcutaneous injection of RA into the dorsal skin of mice alleviates dibutyl square acid (SADBE)-induced pruritus and skin inflammation by inhibiting the MRGPRX2-PLCγ1PKC-NF-κB axis, which is involved in mast cell activation." (PMID 39684446, 2024). "Results indicate GE1111’s effects on MRGPRX2 inhibition, which contributes to anti-pruritic outcomes; alternative itch models (e.g., acute/chronic) could further validate broad anti-itching efficacy." (PMID 41296102, 2025). "Furthermore, PCG showed minimal antagonistic activity against other pruritus-related GPCRs (H1R, H4R, TGR5, 5HT2A, 5HT2B, and MRGPRX2), even at a high concentration of 30 μM." (PMID 41009488, 2025). "The number of MRGPRX2+ cells did not correlate with disease severity, disease duration, pruritus, QoL impairment, eosinophil numbers, and serum levels of tryptase, total IgE, substance P, IL-31, eosinophilic cationic protein, and major basic protein." (PMID 38022672, 2023).
mastocytosis (6 papers, 2021 to 2024). A clonal myeloproliferative neoplasm characterized by the proliferation and accumulation of neoplastic mast cells in one or multiple organs or organ systems. "Substance P (SP)-mediated activation of human skin MCs via MRGPRX2 is implicated in the pathogenesis of chronic urticaria and mastocytosis." (PMID 35126366, 2021). "Increased numbers of MRGPRX2-expressing (MRGPRX2+) cells have been reported in lesional skin of patients with various skin disorders including mastocytosis, chronic urticaria and chronic prurigo." (PMID 38022672, 2023). "MCs are known to express MRGPRX2, and MC accumulation is a typical finding in mastocytosis in the skin." (PMID 35958589, 2022). "Increased MRGPRX2 expression on skin MCs has been recently reported in patients with maculopapular cutaneous mastocytosis and suggested as a possible driver of mastocytosis pathogenesis." (PMID 35958589, 2022). "As of yet, little is known about the clinical relevance of MRGPRX2 and its agonists in patients with mastocytosis, including indolent systemic mastocytosis (ISM)." (PMID 35958589, 2022). "Recently, the expression of Mas-related G protein-coupled receptor X2 (MRGPRX2), a receptor of mast cell (MC) responsible for the IgE-independent non-histaminergic itch, has been shown in lesional skin of patients with pruritic skin diseases, including chronic urticaria, prurigo, and mastocytosis." (PMID 38022672, 2023). "In contrast to nondepolarizing NMDAs, Succinylcholine does not interact with MRGPRX2 and is considered safe for patients with mastocytosis." (PMID 38247999, 2024). "Vancomycin and fluoroquinolones may induce reactions through non-IgE mechanisms, potentially MRGPRX2, and their use should be limited in patients with mastocytosis." (PMID 38247999, 2024).
allergic asthma (5 papers, 2020 to 2025). A asthma with a basis in a pathological type I hypersensitivity reaction. "Based on these findings, we hypothesized that SP contributes to allergic asthma by activating MCs via MRGPRX2." (PMID 39483467, 2024). "Additionally, its potential role in modulating allergic asthma is being increasingly recognized and it now appears that human lung mast cells express MRGPRX2." (PMID 34071807, 2021). "Thus, it is possible that upon allergen challenge, SP is released from sensory nerves and activates MRGPRX2-expressing lung mast cells to mediate bronchoconstriction and Th2-mediated immune responses, resulting in mild allergic asthma." (PMID 34071807, 2021).
psoriasis (5 papers, 2021 to 2024). An autoimmune condition characterized by red, well-delineated plaques with silvery scales that are usually on the extensor surfaces and scalp. "In psoriasis, we observed an increase in MRGPRX2 expression, likely linked to elevated MC numbers in the inflammatory skin disease." (PMID 39435146, 2024). "Lastly, we demonstrate that in inflammatory skin conditions like psoriasis, the number of MRGPRX2+ MCs is increased, and during in vitro skin reinnervation, MRGPRX2+ MCs preferentially reside in proximity to and migrate toward SP+ nerve fibers (NFs)." (PMID 39435146, 2024). "In a recent study, increased MRGPRX2 mRNA expression in pruritic skin of patients with AD and psoriasis was demonstrated as well." (PMID 33681256, 2021). "Recently, researchers have shown an increased interest in MRGPRX2 in terms of pruriceptive receptor and its involvement in pruritic diseases like AD or psoriasis." (PMID 33681256, 2021). "Notably, the expression of MRGPRX2 in skin MCs was also heterogeneous, and the percentage of MCs expressing MRGPRX2 (healthy 45.40 ± 16.30%, psoriasis 39.65 ± 12.29%) was similar to that of mature blood derived MCs (46.82 ± 28.66%)." (PMID 39435146, 2024). "The density of MRGPRX2+ MCs was significantly correlated with psoriasis severity, although the percentage of MRGPRX2+ MCs was not increased in psoriasis indicating that changes in MRGPRX2 density are likely due to changes in overall MC numbers as we have previously demonstrated." (PMID 39435146, 2024). "To investigate whether MRGPRX2+ MC numbers correlate with inflammatory conditions and thus indicate that MRGPRX2 is a marker of MC accumulation in the tissue, we have investigated MCs in psoriasis skin lesions and compared them to healthy skin." (PMID 39435146, 2024). "While these findings could indicate a prominent role of TACR1 in MC-dependent itch in psoriasis, we cannot exclude the contribution of the MRGPRX2-induced signalling pathway, as this receptor is known to be constitutively and preferentially highly expressed in skin MCs." (PMID 37681909, 2023). "In our study, TACR1 was upregulated in psoriasis MCs, while MRGPRX2 displayed no significant changes in its expression." (PMID 37681909, 2023).
inflammatory skin disease (4 papers, 2024 to 2025). Inflammatory skin disorders covers a broad category that includes many conditions ranging in severity, from mild itching to grave medical health complications These disorders are common in people of all ages and races. "The latest research on the role of MRGPRX2 in skin inflammatory diseases yielded compelling insights into these complex immunological processes." (PMID 38334612, 2024). "Previous research has identified and confirmed that there is a role for MRGPRX2 in inflammatory skin diseases." (PMID 38334612, 2024). "These candidates, which exhibit varying degrees of efficacy in in vitro and animal models, hold promise for addressing MRGPRX2-mediated immune responses in skin inflammatory diseases." (PMID 38334612, 2024). "However, primarily, it should be confirmed which specific elicitors of MRGPRX2-mediated reactions occur in the context of inflammatory skin diseases such as AD and CU." (PMID 38334612, 2024). "Therefore, the involvement of MRGPRX2 in inflammatory skin diseases is suggested." (PMID 38535499, 2024). "In fact, both MRGPRX2 and MCs may be important in inflammatory skin diseases without an allergic background." (PMID 39996342, 2025).
migraine (4 papers, 2021 to 2024). "While the precise mechanisms underlying how PACAP activates Mgprb2 and MRGPRX2 on mast cells to induce migraine pain remains an area of investigation, there is a possibility that their degranulation could result in the expansion of meningeal arteries." (PMID 38198852, 2024). "Recently, MrgprB3, which is thought to be the rat homologue of human MrgprX2, has also been studied for its involvement in migraine." (PMID 37232078, 2023). "High-affinity MRGPRX2 inhibitors are expected to be applied to areas where there are few effective therapeutic agents, such as postoperative pain, migraine, and drug-induced acute pseudoallergic reactions." (PMID 34831128, 2021). "Importantly, in vivo, dural application of PACAP resulted in migraine-like pain behavior in MRGPRX2-overpressing mice, significantly more than in control animals." (PMID 38198852, 2024). "This circumstantial evidence enables us to imagine that MRGPRX2 in MC may be deeply involved in the induction of neurogenic inflammation in migraine." (PMID 34831128, 2021). "In particular, MrgprB2 (human homologue MrgprX2) may be a promising target for migraine treatment." (PMID 37232078, 2023). "The data presented here demonstrate, for the first time, a mouse line that functionally expresses MRGPRX2 in connective tissue mast cells, including meningeal mast cells, and responds to PACAP1-38 to contribute to migraine-like pain." (PMID 37516794, 2023). "Here we identify the mast cell-specific receptor, MrgprB2, and its human homolog, MRGPRX2, in mediating PACAP1-38-induced migraine-like pain." (PMID 37516794, 2023). "Furthermore, using a newly generated transgenic mouse line, we show that MRGPRX2 is potently activated by PACAP and leads to migraine-like pain." (PMID 37516794, 2023). "Using a transgenic MRGPRX2 mouse, we observed significant increases in PACAP-induced migraine-like pain behavior in MRGPRX2+ mice vs mice lacking the receptor." (PMID 37516794, 2023).
systemic mastocytosis (3 papers, 2022 to 2026). Systemic mastocytosis (SM) comprises a heterogeneous group of rare acquired and chronic hematological malignancies that are related to an abnormal proliferation of mast cells in tissue, including bone marrow, with or without skin involvement. "In patients with indolent systemic mastocytosis, the number of MRGPRX2+ cells correlated with eosinophil number." (PMID 38022672, 2023). "Similarly, the number of MRGPRX2+ cells did not correlate with the clinical and laboratory characteristics of patients with indolent systemic mastocytosis." (PMID 38022672, 2023).
allergic rhinitis (2 papers, 2024 to 2025). Inflammation of the nasal mucous membranes caused by an IgE-mediated response to external allergens. "However, the specific mechanisms by which MRGPRX2 affects allergic rhinitis remain to be elucidated." (PMID 39185421, 2024).
angioedema (2 papers, 2022 to 2024). Swelling involving the deep dermis, subcutaneous, or submucosal tissues, representing localized edema. "IgE-independent mechanisms of mast cell activation may also be involved in angioedema caused by drugs such as vancomycin or fluoroquinolones via Mas-related G protein-coupled receptor X2 (MRGPRX2) or non-steroidal anti-inflammatory drugs via alterations in arachidonic acid metabolism." (PMID 36238930, 2022).
basophilic leukemia (2 papers, 2019 to 2021). "Human MCs such as LAD-2 cells endogenously express MRGPRX2, while rat basophilic leukemia RBL-2H3 cells, and murine bone marrow mononuclear cells do not express MRGPRX2." (PMID 33925682, 2021). "Using pertussis toxins and YM-254890, we demonstrated that SP induces Ca2+ mobilization and degranulation via both the Gαi and Gαq family of G proteins in rat basophilic leukemia (RBL-2H3) cells stably expressing MRGPRX2." (PMID 31652731, 2019). "Rat basophilic leukemia (RBL-2H3), a commonly used model for MC activation, does not endogenously express MRGPRX2." (PMID 31652731, 2019).
contact dermatitis (2 papers, 2021). An inflammatory skin condition caused by direct contact between the skin and either an irritating substance or an allergen. "The study showed that MrgprB2/MRGPRX2 had an effect on Thimerosal-induced mast cell degranulation as well as the pseudoallergic response in mice—thus, it may play an important role in contact dermatitis in humans." (PMID 34279428, 2021). "A new connection is being discovered between MRGPRX2 and contact dermatitis." (PMID 33922606, 2021).
cutaneous mastocytosis (2 papers, 2022 to 2023). Cutaneous mastocytosis is a term referring to a group of diseases characterized by abnormal accumulation and proliferation of skin mastocytes. "Recently, the expression of the mast cell (MC) receptor Mas-related G protein–coupled receptor X2 (MRGPRX2) has been detected in lesional skin of adult patients with cutaneous mastocytosis." (PMID 35958589, 2022).
Headache (2 papers, 2023 to 2024). Cephalgia, or pain sensed in various parts of the head, not confined to the area of distribution of any nerve. "Nevertheless, our finding that activation of the PACAP38-MrgprB2/MRGPRX2 pathway causes headache behaviour suggests that migraine headache is a warning sign of stress-induced homeostatic imbalance." (PMID 38802819, 2024). "Numerous peptides can interact with MrgprB2/MRGPRX2, and a variety of triggers can initiate headaches." (PMID 38802819, 2024).
idiopathic pulmonary fibrosis (2 papers, 2024 to 2025). Idiopathic pulmonary fibrosis (IPF) is a nonneoplastic pulmonary disease that is characterized by the formation of scar tissue within the lungs in the absence of any known cause. "This study reveals that the proinflammatory chemokine CXCL14 activates MAS-related G protein-coupled receptor MRGPRX2; these results provide a rational basis for the future development of idiopathic pulmonary fibrosis therapies." (PMID 38184723, 2024). "In conclusion, we discovered MRGPRX2 as a target of the orphan proinflammatory chemokine CXCL14 both of which are upregulated in pulmonary fibrosis." (PMID 38184723, 2024).
inflammatory bowel disease (2 papers, 2026). A spectrum of small and large bowel inflammatory diseases of unknown etiology. "We also review emerging data indicating that HαT may act as a disease modifier in inflammatory bowel disease (IBD); increased α-tryptase gene dosage is associated with intestinal MC activation and increased expression of MRGPRX2." (PMID 42058624, 2026).
prurigo (2 papers, 2023). A name applied to several itchy skin eruptions of unknown cause. "Moreover, the number of cells expressing MRGPRX2 in skin lesions and serum levels of MRGPRX2 correlate with prurigo severity, itch intensity, and/or impaired quality of life." (PMID 38077377, 2023).